IL21 (interleukin 21)
Diseases named in the same sentence as IL21 in open-access papers (continued):
Sharing a sentence is not in itself a finding about the gene and the disease.
infection (continued). "Early S‐specific T‐cell responses—particularly polyfunctional, IL‐21‐producing Tph cells—play a key role in sustaining durable antibody levels post‐infection, offering insights for future vaccine strategies and understanding long‐term immunity." (PMID 41427434, 2025). "The early presence of polyfunctional, IL‐21‐producing Tph strongly correlated with S‐specific IgG and neutralising antibodies early post‐infection and predicted neutralising antibody maintenance a year later." (PMID 41427434, 2025). "In the third infection, IFNγ and IL-21 were once again significantly upregulated at T6 together with TH1-associated chemokine receptors." (PMID 40214640, 2025). "The median pre-infection biomarker level was higher in each instance, and this difference was significant for IL-6 (p = 0.0088) and trending for IL-21, IL-5 and fractalkine (p = 0.0192, 0.0503 and 0.0533 respectively)." (PMID 40862133, 2025). "We observed that nine biomarkers (fractalkine, IFNγ, IL-5, IL-6, IL-10, IL-12, IL-13, IL-21, and TNFα) had significantly increased levels post-infection with subtype C HIV-1 compared to the pre-infection levels." (PMID 40862133, 2025). "M.tb challenge is known to induce interleukin-21 (IL-21), which is significantly upregulated in TB granulomas and essential for control of infection." (PMID 38799468, 2024). "We next investigated the effects of IL-21 on EBV latency gene expression when dosed at day 7 post-infection, the earliest timepoint when B-cells begin to convert to lymphoblastoid physiology." (PMID 38683861, 2024). "To then gain insights into germinal center cytokine effects on EBV-infected primary B-cells, we treated cells at 7 days post-infection with vehicle control, IL-4, IL-15, IL-21, IL-27 or multiple combinations thereof." (PMID 38683861, 2024). "We next tested the effects of IL-15 and IL-21 on EBV latency gene expression at day 10 post-infection." (PMID 38683861, 2024). "We observed that ST-challenged neonatal broilers after 24 h post-infection had significant increases in pro-inflammatory cytokines- IL-6 (p = 0.0025), IL-16 (p = 0.0196), and IL-21 (p = 0.0066)." (PMID 38465263, 2024). "Taken together, our results indicate that IL-21 was produced by CD3γ/δ+ cells and that IL-21/CD3γ/δ+ cells were markedly upregulated in the anterior, middle and posterior intestine after infection with A. hydrophila." (PMID 37759501, 2023). "In respiratory syncytial virus infection, IL-21 inhibits the expression of RORγt and T-bet at the site of infection, resulting in reduced recruitment of Th17 cells and Th1 cells." (PMID 37628738, 2023). "Overall we noticed a significant decrease in IL-21 level at later time points compared to initial time points post infection." (PMID 36707891, 2023). "Prior studies examining the TFH response after infection with the nematode Nb showed that TFH cells change over time following infection and proceed from producing IL-21 alone (TFH21 cells) to producing primarily IL-4 (TFH4 cells)." (PMID 37575256, 2023). "Overall we noticed a decrease in IL-21 level at later time points compared to initial time points post infection." (PMID 36707891, 2023). "One of the most crucial attributes of Mφ responses lies in their ability to secrete cytokines, so we further analyzed how IL-21/IL-21R influence the Mφ polarization after infection." (PMID 37628738, 2023). "The IL-21 level was further decreased significantly to 74%, p < 0.0042 at 12 h compared to 6 h post infection." (PMID 36707891, 2023). "It has also been shown that il21 is induced by viral hemorrhagic septicemia virus in the kidney of rainbow trout at the early stage of infection." (PMID 37759501, 2023). "In particular, IL-21 is a critical regulator of antibody-mediated immunity in response to infection or vaccination, specifically through the action of Tfh-derived IL-21 on GC B cells, which promotes their function and survival." (PMID 37583704, 2023).
infection (continued). "BCL6 mRNA and IL21 were increased with the infection (p < 0.01 and p < 0.05, respectively) on day 5 PI." (PMID 37593762, 2023). "CD14+ neutrophils, which mainly increased in number during the recovery stage of infection, were revealed to have a stronger ability to produce cytokines, especially IL-10 and IL-21, than their CD14− counterparts." (PMID 37705063, 2023). "Normalization of the data to each specimen’s untreated control reveals that 10/13 tonsil samples show some level of increased infection upon treatment with 100pg/ml of IL-21." (PMID 36569889, 2022). "Transcriptomics analyses in the hamster model of infection have identified mRNAs for regulatory cytokines (IL-4, IL-10, and IL-21), arginase (Arg1), and low nitric oxide production by macrophages as key factors of immunopathology and parasite persistence." (PMID 35384718, 2022). "Recent researches revealed that IL-21/IL-21R plays both proinflammatory and anti-inflammatory roles in infection and inflammation." (PMID 35693111, 2022). "IL-21/IL-21R was documented to participate in the regulation of multiple infection and inflammation." (PMID 35693111, 2022). "Similar to Il21−\− studies, blockade of IL-21R from days 4–9 after infection with P. berghei line XAT, a low virulence strain of P. berghei, results in a significant decrease in GC B cells, though GC B cells are still detectable by flow cytometry." (PMID 35631044, 2022). "In conclusion, the higher level of effective T-cell response with IFN-γ, IL-17A, and IL-21 contributes to resolved infection outcome, while higher levels of suppressive T-cell response with IL-10 result in HBV chronicity." (PMID 35464946, 2022). "To further address the early stages of the IL-21 response during infection, we examined expression of the IL-21 receptor (IL-21R) in primary human tonsil B lymphocytes at baseline (day 0) in each tonsil specimen." (PMID 36569889, 2022). "Among those, the highest fold changes in the infected liver were for Nos2 (log2FC > 10), Ifnγ (log2FC > 8), Tnf (log2FC > 5), and Il21 (log2FC > 6.6), denoting the sustained high inflammatory environment in this tissue during late infection." (PMID 35384718, 2022). "It would seem that IL21 and IFNγ are important early in the infection, while a week after acute infection the cells take on a plasma cell precursor signature." (PMID 36380692, 2022). "Comparing untreated and IL-21 treated cultures within infection conditions revealed a significant effect of IL-21 treatment on IL-21+ plasma cells only in the KSHV-infected cultures (left)." (PMID 36569889, 2022). "Our results show that IL-6 from B cells is an important factor for local Tfh formation and IL-21 production during the early phase of infection." (PMID 35154093, 2022). "IL-21 produced by CD4+ T cells during LCMV Cl 13 infection and signaling through the IL-21 receptor is crucial for maintaining antiviral CD8+ T cell responses and ensuring clearance of infection." (PMID 34696381, 2021). "Though reduced, IL-21 produced during the chronic phase can provide help to CD8+ T cells to resolve the infection." (PMID 34721405, 2021). "We found two different populations, one B220lo and the other B220high that secreted IL-21 during the acute stage of the infection." (PMID 35071041, 2021). "IL-6 shares functional features with IL-21, and it is produced in certain tissues (bone, lung, liver, adipose tissue, muscle) to fulfill homeostatic functions as well as in response to infection, cancer and tissue injury." (PMID 34234771, 2021). "After 2 weeks of infection with 50 trypomastigotes of T. cruzi (RA strain), we detected an increase in IL-21 producing B220+ cells." (PMID 35071041, 2021). "Other possible facilitators of IL-17A expression include IL-6, as it is increased during MHV68 infection, or IL-21, as IL-21 signaling is required for efficient establishment of MHV68 latency and germinal center response in infected mice." (PMID 33824206, 2021).
infection (continued). "IL-17 is a proinflammatory cytokine that mobilizes monocytes and neutrophils to the site of infection, and the activation of IL-17 successively activates several downstream cytokines and chemokines, including IL-1, IL-6, IL-8, IL-21, TNF-β, and MCP-1." (PMID 35054427, 2021). "The expression of il-21 and inf-γ represents the second pattern, where the expression of both genes was increased upon infection but was unaffected by inositol." (PMID 34566956, 2021). "There seems to be a difference in the amount of IL-21 produced depending on the infection status and the sample." (PMID 34502427, 2021). "Overall, signaling through the shared IL-6 family receptor, gp130, was crucial for promoting an antiviral response and producing IL-21 during LCMV Cl 13 infection." (PMID 34696381, 2021). "In this study, the percentage of IL-6, IL-21, IL-1α, IL-17 γδT cells increased significantly after infection (p < 0.05)." (PMID 33588839, 2021). "Inflammatory cytokines such as IFN-γ, TNF-α, and IL-21 have been shown to play a critical role in the severity of SARS-CoV-2-mediated infection." (PMID 34199203, 2021). "The levels of inflammatory cytokines decreased sharply at about 8 weeks post-infection, at which time the levels of IL-10 and IL-21 peaked." (PMID 33330140, 2020). "Both Th1-like IFN-γ+IL-21- and hybrid IFN-γ+IL-21+ Teff were significantly increased in the short-term infection in Bcl6 TKO mice compared with WT, showing a larger effect of Bcl6 on IFN-γ expression in shorter stimulation than longer." (PMID 32634740, 2020). "The levels of IFN-γ, IL-12, and IL-6 in mouse serum peaked at 6 weeks post-infection, and IL-10 and IL-21 levels peaked at 8 weeks post-infection." (PMID 33330140, 2020). "Cytokines decreased sharply at 8 weeks post-infection, while the levels of IL-10 and IL-21 increased significantly." (PMID 33330140, 2020). "IL-21 producers are thought to be essential for CD8+ T cell differentiation into resident memory T cells in the brain after infection with MuPyV." (PMID 33120989, 2020). "In several infection models, IL-21 has been identified as the CD4 T help needed for formation and survival of TRM and TEX." (PMID 32971931, 2020). "Unbiased t-distributed stochastic neighbor embedding analysis gated on CD4+ T cells shows the small cluster of GC Tfh (Bcl6hiCXCR5hiPD-1hi) and the larger islands of hybrid Th1/Tfh cells (IFN-γ+IL-21+) generated in response to both infections." (PMID 32634740, 2020). "Using flow cytometry, we measured GC B cell numbers and the expression of CXCR5, PD-1, IFN-γ, IL-21, T-bet, and Bcl6 in Teff for the first 30 days of infection." (PMID 32634740, 2020). "CD4 T cells in the brain produce IL-21 during early infection by the gliatropic JHMV coronavirus and CD8 T cells upregulate the IL-21 receptor (IL21R); notably, IL21R−/− CD8 T cells have impaired granzyme B and IFNγ production." (PMID 32971931, 2020). "Recently, they have demonstrated that ChAT is induced in both CD4+ and CD8+ T cells during infection in an interleukin-21 (IL-21)-dependent manner and is key for overcoming infections." (PMID 32595942, 2020). "Although IL‐21 is not required to activate Tfh cells in P. chabaudi infections, Tfh cells are an important source of IL‐21 and are also essential to generate class‐switched antibody responses and clear the infection." (PMID 31733075, 2020). "As Tcm and Tfh generation seems to be linked, we tested if limiting the duration of infection by drug treatment would alter the T cell cytokine profile away from IFN-γ+IL-21+ hybrid Th1/Tfh." (PMID 32634740, 2020). "Further analysis of the donor cells recovered from the spleen of infected tcrb-/- mice indicated that a similar proportion and number of the WT and Icos-/- donor T cells produced IFN-γ and IL-21 in response to infection." (PMID 32348365, 2020). "Potential similarities are also seen with a population of IL-21-producing CD4+ T cells in the CNS after infection with mouse polyoma virus (MuPyV)." (PMID 33120989, 2020).
infection (continued). "IL-21 also induced expression of the CCL2 gene, which encodes MCP1, a chemokine that recruits additional innate cells to sites of infection." (PMID 30969166, 2019). "In recent years, however, it has been observed that IL-21 is induced in the periphery and mucosal tissues of humans and mice after infection with some parasites." (PMID 31867283, 2019). "In contrast, it appears that the IL-21/IL-21R signaling axis also played critical roles in the development of TH2 immune response following infection with the intestinal luminal nematodes, Nippostrongylus brasiliensis and H. polygyrus." (PMID 31867283, 2019). "IL-21 was detectable following infection of mice with a natural murine intestinal nematode, Heligmosomoides polygyrus." (PMID 31867283, 2019). "Previously, we found that IL-21 promotes the pathologic immune response to infection with Pneumonia Virus of Mice (PVM), which is highly related to human Respiratory Syncytial Virus (RSV), with enhanced neutrophil recruitment and acute respiratory distress." (PMID 30969166, 2019). "The peak of IL-21 production in the distal colon of WT mice infected with C. rodentium occurred 9 days p.i., when the infection was at its peak." (PMID 30818341, 2019). "During chronic or prolonged infections, many have observed the production of IL-21 by additional CD4+ T cell subsets including TFH and TH17 cells." (PMID 31379821, 2019). "Consistent with an inverse relationship between IL-21 signaling and IFNα levels following infection with MRSA, IFNα levels were elevated in both serum and BAL fluid of the Stat3 mutant mice." (PMID 30969166, 2019). "Concerning the modulation by PRRSV of cytokine expressions related to B cell homeostasis, BAFF was found to be upregulated in LN MΦ upon infection whereas levels of IL21 and IL10 were unchanged." (PMID 31130951, 2019). "We used RT-PCR to confirm IL-21-induced expression of Gzma and Gzmb mRNAs in the lung at 7 hr after infection, and IL-21-induced granzyme B and IFNγ protein production was detected by ELISA in bronchoalveolar lavage fluid at 7 hr after infection." (PMID 30969166, 2019). "IL-21 is induced during human infections with Plasmodium falciparum and Plasmodium vivax, as well as following vaccination against P. falciparum." (PMID 31867283, 2019). "(A, B) Intra-tracheal infection with the USA 300 strain of MRSA induced a significant increase in pulmonary Il21 mRNA (A) and IL-21 protein (B) 24 hr after infection." (PMID 30969166, 2019). "To investigate the mechanism by which IL-21 enhanced MRSA killing, we next performed RNA-Seq analysis using RNA from total lung tissue from mice that were treated with PBS or IL-21 prior to infection with MRSA." (PMID 30969166, 2019). "Although IL-21 treatment significantly reduced the MRSA titer in the lung 24 hr after infection of isotype control-treated mice, it had less of an effect on MRSA clearance in the neutrophil-depleted mice." (PMID 30969166, 2019). "An interesting study in SIV-infected rhesus macaques probed the question from the opposite perspective and sought to determine the kinetics of IL-21 expression during infection." (PMID 31379821, 2019). "The most critical factors highlighted during the analysis of the Treatment response model include IL-10, IL-21, IL-12, IL-2 which determine the treatment outcome in terms of clearance of infection by modulating pro-inflammatory response." (PMID 29891859, 2018). "Our IL-10+IL-21+ CD4-depletion experiments indicate that early inflammatory signals propagated during the first few weeks of LCMV Cl13 infection are necessary for the formation of IL-10+IL-21+Tfh cells." (PMID 30487586, 2018). "Animals infected with the NM showed a decreased level of pro-inflammatory cytokines TNF-α, IFN-ɣ and IL-21 throughout the course of the infection and higher levels of IL-10." (PMID 28650996, 2017).
infection (continued). "Immunohistochemical results showed that the percentage of IL-21 positively staining cells was increased at 4 weeks post-infection compared to that before infection and reached peak at 12 weeks post-infection before decreasing gradually." (PMID 29192177, 2017). "Blocking DENV RNA replication and infection of DCs with DENV RNA replication inhibitor SDM25N abolished the formation of IL-21-secreting CXCR5+PD-1+Bcl-6+ TFH cells." (PMID 29186193, 2017). "During Schistosoma haematobium and Echinostoma caproni infection, the Th17-related cytokines (IL17, IL21 and IL23) were associated with protection against parasite re-infection/infection respectively." (PMID 27661612, 2016). "IL-21 signaling can inhibit the expansion of Tregs both in vitro as well as after infection with LCMV." (PMID 31557986, 2016). "Here, we demonstrate that in vivo infection with M. haemolytica results in increased expression of IL-17, IL-21 and IL-22." (PMID 26942409, 2016). "We observed that IL-21R−/− cells lag behind WT cells starting 13 days post-infection, indicating that IL-21 signaling promotes efficient CD8+ T cell priming." (PMID 27819295, 2016). "A single study measured bacterial growth in IL-21−/− mice following infection, and found comparable bacillary loads in WT and KO mice through day 200 post-infection." (PMID 27819295, 2016). "By day 120–140 post-infection, the pattern of cytokines co-expressed with IL-21 resembled that of naïve WT C57BL/6 mice." (PMID 25763578, 2015). "By contrast, cytokines involved in Th17 signal transduction, such as IL-17A, IL-17F or IL-21, were highly up-regulated after infection, and the Th17 pathway is known to contribute to inflammation and influx of neutrophils to the site of infection." (PMID 25719526, 2015). "IL-21 also suppressed infection by primary clade A (92UG029) and clade B (HC4 and 2044) HIV-1-subtype-infected HLACs indicating a broad antiviral activity." (PMID 26108174, 2015). "At day 32 post-infection, the numbers of B cells in the spleen of Il21-/- and Il21r-/- mice were reduced compared to WT C57BL/6 controls, and this was reflected in the numbers of mature (M), transitional 1 (T1) and transitional 2 (T2) B cells." (PMID 25763578, 2015). "IL-21 has been shown to be critical for isotype-switched antibody production and parasite clearance in this infection." (PMID 26646149, 2015). "The frequency of these triple producers increased with the progression of the infection until day 32 post-infection, when a maximum of approximately 30% of IL-21-producing CD4+ T cells co-expressed IFN-γ and IL-10." (PMID 25763578, 2015). "In a similar way, IL-21 signaling was required to control and eliminate a P. yoelii 17X(NL) infection." (PMID 25763578, 2015). "Taken together, these data demonstrate a central role for IL-21 signaling in the resolution of erythrocytic-stage P. chabaudi and P. yoelii 17X(NL) infections." (PMID 25763578, 2015). "We show that IL-21 signaling in B cells is critical for efficient establishment of MHV68 infection and is required for efficient access to both the germinal center and plasma cell fractions." (PMID 25875847, 2015). "By 120 days post-infection, the frequency and total numbers of IL-21-producing CD4+ T cells in the spleen were comparable to those observed in naïve WT C57BL/6 mice." (PMID 25763578, 2015). "In accordance with the kinetics observed for IL-21 mRNA expression, the percentage and total number of IL-21-producing CD4+ T cells in the spleen increased early after infection." (PMID 25763578, 2015). "During the process of infection, expression level of IL-21 produced by Tfh cells is much higher than IL-4." (PMID 26503442, 2015). "chabaudi infection, there was a striking increase in the spleen by day 7 post-infection, when IL-21 mRNA levels were approximately 130-fold higher than the basal level." (PMID 25763578, 2015). "ICOSL KO mice displayed reduced levels of IL-21 compared to WT mice, particularly at 7 weeks post-infection." (PMID 25590646, 2015).